WNK2 (WNK lysine deficient protein kinase 2)
Diseases named in the same sentence as WNK2 in open-access papers (continued):
Sharing a sentence is not in itself a finding about the gene and the disease.
tumor (29 papers, 2012 to 2026). "The WNK2 gene on OAR2 is associated with tumour suppressive function in humans, and when this gene is knocked down, it leads to accelerated tumour growth in mouse models." (PMID 37932811, 2023). "In contrast, low expression of WNK2 is significantly associated with early tumor recurrence and poor OS in HCC patients." (PMID 36123332, 2022). "WNK2, for example, is a negative regulator of cell proliferation and its hypermethylation is related to loss of gene expression and, accordingly, to tumor aggressive behavior." (PMID 35892898, 2022). "In a study of 736 HCC patients, somatic mutation and copy number loss occurred in 39 and 200 cases, respectively, and the low expression of WNK2 is associated with poor OS and early tumor recurrence." (PMID 36123332, 2022). "As a negative regulator of cell proliferation, loss of WNK2 is likely associated with more aggressive tumor growth." (PMID 31970090, 2019). "Furthermore, the inactivation of WNK2 also led to the infiltration of tumor-associated macrophages, which promoted tumor growth and metastasis." (PMID 37627077, 2023). "WNK2 upregulated POU5F1B mRNA and protein levels, while POU5F1B overexpression reversed the tumor-suppressive effects caused by WNK2 depletion." (PMID 41628111, 2026). "Silencing LINC00858 induces autophagy, apoptosis, and senescence in vitro and inhibits tumor development in vivo by preventing methylation of the WNK2 promoter and increasing WNK2 expression." (PMID 40723786, 2025). "cg13563298 is intragenic to WNK2, a tumour suppressor, and lastly, cg03758477 is intragenic to SEC14L1found to be a prognostic factor in breast cancer38and is also associated with endometrial serous carcinoma39and prostate cancer." (PMID 39622952, 2024). "In HCC, loss-of-function mutation of WNK2 leads to the activation of ERK1/2 MAPK signaling, contributing to tumor growth and pulmonary metastasis." (PMID 36123332, 2022). "Immunohistochemistry revealed the positive correlation between WNK2 expression and tumor pathological grade." (PMID 35549643, 2022). "To date, WNK2 acts as a tumor suppressor in gliomas and hepatocellular, gastric, breast, colon cancers." (PMID 35549643, 2022). "Loss of WNK2 expression leads to the activation of oncogenic signaling pathways, such as ERK1/2, JNK-MMP2/9 and Rac1, thus enhancing tumor growth and metastasis." (PMID 36123332, 2022). "And WNK2 expression is positively correlated with tumor malignancy and negatively correlated with patient prognosis, which not only facilitates OC progression both in vitro and in vivo but also reverses the cancer-suppressive effects of miR-324-3p." (PMID 35549643, 2022). "In this study, we demonstrated the tumor-promoting role of WNK2 in OC and found that the expression of WNK2 was exactly the opposite of that of miR-324-3p in OC cells and tissues." (PMID 35549643, 2022). "Four genes (EPHA7, SOCS2, SYNM, WNK2) are tumor suppressor genes whose hypermethylation is a common mechanism of downregulation." (PMID 28927421, 2017). "In the stage III network, WNK2, a widely known tumor suppressor, is underexpressed." (PMID 35936681, 2022). "The serine/threonine kinase WNK2 (with no lysine protein kinase 2) acts as a tumor suppressor in GBM and is associated to carcinogenesis-related pathways." (PMID 32093151, 2020). "However, we observed a positive correlation between WNK2 levels and tumor malignancy (p < 0.05)." (PMID 35549643, 2022). "In cervical cancer, miR-18a is found to directly target and inhibit WNK2, leading to the activation of ERK1/2-PD-L1 signaling and promoting tumor growth and invasion." (PMID 36123332, 2022). "Some of the hypermethylated genes in TET2-wt CMML have been directly or indirectly related to cell cycle arrest, tumor suppression or myeloid differentiation (ZIC1, WT1, WNK2, MRPL41, POU4F2)." (PMID 22328940, 2012).
tumor (continued). "Examples are COL4A6, WNK2 and STK32B whose roles have been assigned in processes such as prevention of early invasion stages, negative regulation of epidermal growth factor receptor signaling and opposite correlation with tumor size, respectively." (PMID 33691672, 2021). "Genes related to cancer pathways were downregulated upon atezolizumab treatment, including angiogenic factors for tumor vascularization (TNK1, AREG and KDR), proto-oncogenes (RET and MET) and tumor cell survival/migration/invasion (CDH1, RARA, WNK2, WNT4A, WNT9A, TGFB2, EGF, and LAMA3)." (PMID 32616706, 2020). "Since PTEN, WNK2, SOX6, BTG3, and RBSP3 have putative miR-18a-binding sites in their 3′-UTRs and act as tumor suppressors in CC, we hypothesized that miR-18a enhances PD-L1 expression via targeting these candidate targets." (PMID 29855617, 2018). "Conversely, WNK2, RUSC2, CYP3A4, and RGN, among the significantly downregulated genes in the non-tumor iP organoids, have been described as tumor suppressors downregulated in HCC." (PMID 34328417, 2021).
cancer (17 papers, 2015 to 2025). A tumor composed of atypical neoplastic, often pleomorphic cells that invade other tissues. "There were 12 genes mutated in 30% of patients, of which only WNK2 belonged to the COSMIC Cancer Gene Census (Tier 1 or Tier 2)." (PMID 37920164, 2023). "At the COSMIC Cancer Gene Census gene level, CACNA1D, PIK3CA, and WNK2 mutations belonged to the dMMR-like type of NECC." (PMID 37920164, 2023). "MiR-93, miR-130a, miR-210a, miR-524a, and miR-620 are found to directly target oncogenic WNK1/3 or antitumor WNK2, thus affecting cancer progression." (PMID 36123332, 2022). "The low expression levels of WNK2 have been found in several kinds of cancer, mainly induced by aberrant methylation in the 3’CpG island of gene promoter." (PMID 36123332, 2022). "A transcriptional repressor chromobox protein homolog 8 (CBX8) can directly bind to the WNK2 promotor and repress its activity in human cancers." (PMID 36123332, 2022). "In GC, WNK2 can inhibit the tumorigenicity of cancer cells by preventing the phosphorylation of ERK1/2 and p38." (PMID 36123332, 2022). "Given the importance of WNK2 in cancer context, it is important to identify its upstream and downstream targets and determine how they influence WNK2 function." (PMID 25596741, 2015). "In addition, several kinds of ncRNAs are involved in the inactivation of WNK2 to affect cancer progression (see details in part “WNKs and ncRNAs in cancer”)." (PMID 36123332, 2022). "In addition, recent studies have found that lncRNA LINC00858 can directly repress the expression of WNK2 in cancer cells and contribute to cancer progression." (PMID 36123332, 2022). "The role of WNK2 is controversial in regulating autophagy in cancer." (PMID 36123332, 2022). "WNK kinase family fusions (WNK1 and WNK2) were also detected in multiple cancer types." (PMID 29617662, 2018). "Moreover, the OC cancer-promoting role of WNK2 has also been demonstrated." (PMID 35549643, 2022). "PTEN, SOX6, WNK2, BTG3, and RBSP3 protein expression was decreased in miR-18a-overexpressing CC cells but was increased in miR-18a-silenced cancer cells." (PMID 29855617, 2018). "Considering that the expression levels of WNK2, CYP1A1, PAX5, XRCC1, and TGM3 have been reported to be closely related to the development of cancer, we then detected the expression levels of these genes in SK-MES-1 and A549 cells after transfection of circFLNA and miR-486-3p mimic." (PMID 33500536, 2022).
WNK2 also shares sentences with these, for which no sentence is quoted: gastric cancer (2 papers); bacterial infections (1); Cerebral ischemia (1); Cirrhosis (1); digestive system cancer (1); familial meningioma (1); fibrosarcoma (1); fungal infection (1); hairy cell leukemia (1); infection (1); liver cancer (1); marginal zone lymphoma (1); multiple myeloma (1); ocular hypertension (1); pancreatic adenocarcinoma (1); polyposis (1); pyoderma gangrenosum (1); Stroke (1); triple-negative breast carcinoma (1); virus infection (1).